CD2 (CD2 molecule)
Diseases named in the same sentence as CD2 in open-access papers (continued):
Sharing a sentence is not in itself a finding about the gene and the disease.
tumor (continued). "The generation of these tumour-memory NK cells is driven by CD2 ligating CD15 on the tumour cell." (PMID 39599860, 2024). "In HRSdx cells, the decrease in HLA-DR expression could favor the escape from immune system recognition and the increase in CD58, by improving the interactions with CD40L+CD2+ rosetting T cells, and could support tumor cell survival." (PMID 38067159, 2023). "The tumor cells were reactive for T-cell markers (CD2, CD3, CD4, CD10)." (PMID 39092006, 2023). "However, the proportion of CD8 T cells expressing Ki67, a proliferation marker, was much higher in tumours from GFP-Egr2 knockin mice than in CD2-Egr2/3-/- mice." (PMID 36342511, 2023). "Also, T cells interacting with various HPV+ of tumor cells had significantly upregulated CD2 signalling pathways, while both HPV+ and – cells showed similar interactions with endothelial cells." (PMID 35769468, 2022). "Since CD2, CD3D, CD3E, and CXCR6 predict very favorable prognosis in CSCC, we evaluated the association of this new signature at transcriptomic level with the presence of tumor-infiltrating immune cell populations in CSCC." (PMID 34692491, 2021). "Our findings theoretically indicate that increasing the density of CD2 in BRCA tissue might improve immunotherapy efficacy by increasing the tumor immunogenicity and the antitumor immune responses." (PMID 33968066, 2021). "This tumor usually expresses CD2 and CD56 and lacks CD3 (but expresses cytoplasmic CD3ε)." (PMID 34350041, 2021). "Moreover, CD2 protein expression was higher in tumor tissues compared to normal tissues based on the HPA database." (PMID 33968066, 2021). "Thus, CaP coating on the Ti sample promoted the in vitro survival of CD4+ subsets of tumor-derived Jurkat T cells activated by anti-CD2/CD3/CD28 antibodies." (PMID 34279263, 2021). "In addition, we found a positive association between the gene expression level of CD2, CD3D, CD3E, and CXRC6 and the activated fraction of NK cells present in the tumor (CD2: Rho=0.442, CD3D: Rho=0.460, CD3E: Rho=0.423, and CXCR6: Rho=0.401)." (PMID 34692491, 2021). "ITLPD-GI tumor cells typically exhibit a CD2+, CD3+, CD5+, and CD4+ or CD8+ phenotype." (PMID 34830926, 2021). "CD2 expression was associated with tumor size (T stage) to some extent, but not with overall TNM stage, lymph node status (N stage), or distant metastasis (M stage)." (PMID 33968066, 2021). "Typically, tumor cells are CD2+, CD3+, CD4+, CD8−, CD5+, and CD25+, and CD7 is often negative." (PMID 34830926, 2021). "Immunostaining of basal protein markers in As3+ and Cd2+ tumor transplants." (PMID 30550540, 2018). "As visualized in the PCA plot, the transplanted tumors generated from the As3+ and Cd2+-transformed UROtsa cells had similar expression patterns in terms of the 25 marker genes, with all except one UROtsa tumor sample (As#5) that separated from the MIBCs in the first principal component, PC1." (PMID 30550540, 2018). "In contrast, the As3+ and Cd2+-transformed UROtsa cells follow the same pattern over the initial 10 to 13 days, but following disappearance of the nodule, the nodule reforms and continues to grow into a tumor." (PMID 30550540, 2018). "In this context, it has been shown that pre-activation of NK cells with tumor cells through CD2 and its ligand CD15 on tumor cells could enable subsequent lysis of otherwise poorly susceptible target cells." (PMID 30546366, 2018). "Interestingly, a fourfold increase in the percentage of γδ T cells displaying the CD2+CD8α+ phenotype was detected in tumors compared with blood; mean values: 51.1% in tumor isolates in contrast to 12.8% for the PBMC samples." (PMID 29930558, 2018). "Thus, our data shows that the As3+ and Cd2+-transformed cell lines and their derived tumor transplants have gene expression profiles similar to the basal subtype of muscle invasive bladder carcinomas with tumors having enriched squamous features." (PMID 30550540, 2018).
tumor (continued). "In this case, the patient’s tumor was positive for CD2, CD56 and EBER." (PMID 28056876, 2017). "However, despite the high level of CD2 expression in T-lymphocytes, the immune synapses between T-cells and tumor cells are impaired in CLL." (PMID 28881725, 2017). "These tumor cells show positivity for CD2, CD56, EBER-1, and cytoplasmic CD3 epsilon." (PMID 26989539, 2016). "Interestingly, the number of dendritic cells (defined as CD45+Ly-6G-F4/80−CD11b+CD11c+) was higher in tumours from CD2–Tff2 mice versus tumours from the other two groups, suggesting a protective role for dendritic cells." (PMID 26841680, 2016). "AOM/DSS-treated wild-type mice receiving splenic IMCs from untreated CD2–Tff2 mice developed a lower number of tumours and a lower proportion of MDSC but a higher proportion of CD8+ cells in the colon compared with wild-type mice that received splenic IMC from Tff2-null mice." (PMID 26841680, 2016). "For diagnosis, large neoplastic lymphoid cells of IVNKL are restricted to the lumen of small vessels and exhibit the phenotype of a true NK cell, characterized by tumor cells with a CD2+, cytoplasmic CD3ε + and CD56+ immunophenotype and germline configuration of the TCR gene." (PMID 26126576, 2015). "Furthermore, the tumor cells stained positive for CD2, CD3, CD7, CD99, Perforin and, remarkably, CD8." (PMID 22497840, 2012). "Notably, CD58 loss—rather than CD2 deficiency—is a primary mechanism of axis disruption, leading to impaired T-cell cytotoxicity and tumor immune evasion." (PMID 41438981, 2025). "We detected multiple NK cell family receptor encoding genes (e.g., KLRK1, NCR2, CD2, and CD160) which might be critical in mediating anti-tumour immune responses against BLCA because higher expression of these genes was associated with better patient survival probabilities." (PMID 39877370, 2024). "Furthermore, CD2 expression was correlated with 16 types of tumor-infiltrating immune cells (TICs)." (PMID 33968066, 2021). "However, we observed marked differences in tumour development in mice that received wild-type versus TFF2-null versus CD2–Tff2 bone marrow transplants, thus indicating the predominant role of hematopoietic, rather than epithelial, TFF2 expression at least for colorectal carcinogenesis." (PMID 26841680, 2016). "Further challenge with Nalm6-L cells on days seven and twelve resulted in rapid tumor expansion in the CD19-BBζ CAR-T-cell treatment group, while CD19-BBζ + CD2 CAR-T cells continued to effectively restrict tumor growth and prominently improved survival rates." (PMID 40615696, 2025). "After multiple rounds of coculture, the tumor-killing ability of conventional CAR-T cells began to decline noticeably, in contrast to that of CD19-BBζ + CD2 CAR-T cells, which consistently displayed vigorous tumoricidal activity." (PMID 40615696, 2025). "The present study provides the first evidence that CD2 downregulation impairs CTL function and actively reshapes tumor metabolism." (PMID 40859981, 2025). "Twelve studies were on T cell malignancies; they KO CD2, CD3, CD5, or CD7 and simultaneously targeted these antigens on tumor cells." (PMID 41354926, 2025). "The canonical markers EPCAM and KRT19 identified tumor cells, while CD3D, CD2, PTPRC, CD14, AIF1, CD79A, and COL1A2 validated non-tumor cells." (PMID 39955556, 2025). "Functional assays demonstrated that CD2 knockdown inhibited cytotoxic T lymphocyte (CTL) proliferation, activation, and cytotoxicity, leading to impaired tumor cell recognition and enhanced proliferation, migration, and invasion." (PMID 40859981, 2025). "By calculating the remaining tumor cells, we found that EGFR-BBζ + CD2 CAR-T cells exhibited increased overall cytotoxic efficacy against the entire cell population in this mixed model." (PMID 40615696, 2025). "We locate human T cells as cells expressing high PTPRC, CD2, and TRAC and observe areas within the tumor with high variability in the degree of infiltration." (PMID 40081369, 2025).
tumor (continued). "Cytotoxicity assays demonstrated that overexpressing CD2 increased the ability of different CAR-T cells, which employ either 4-1BB or CD28 as the costimulatory domain, to eliminate CD19-low-expressing tumor cells." (PMID 40615696, 2025). "High CD2 expression enhances CTL recognition and cytotoxicity toward tumor cells, whereas CD2 downregulation suppresses CTL proliferation and effector function, compromises immune surveillance, and promotes tumor cell proliferation, migration, and invasion." (PMID 40859981, 2025). "(J–P) Third instar larval eye discs RFP tumor clones generated via ey-Flp; FRT42D Gal80/FRT42D; act5C>CD2>Gal4, UAS-RFP." (PMID 39854621, 2024). "Lymph nodes typically show a monomorphic infiltration of atypical cells, in which tumor cells express CD3 and CD2 and lack CD5 and CD4." (PMID 38892108, 2024). "While the intrinsic costimulatory signal of CD2 in T cells remains important, leveraging its interaction with CD58 on tumors appears to be a pivotal mechanism in the regulation of tumor immunity and requires novel strategies." (PMID 39349829, 2024). "The morphology of the tumor cells appeared blastic with an abnormal immunephenotype CD3+, CD2−, CD5dim, CD4−, CD8+, CD56−, and CD30−." (PMID 39091627, 2024). "In particular, CD2 and CD56 were selected by the model with a coefficient of 0.083 and 0.176, respectively, as positive predictors for tumor occurrence." (PMID 38902710, 2024). "We also observed increased expression levels of immune‐related genes, such as SLAMF7, TNFSF8, BTN3A1, CD2, LGALS9, PRF1, and MX2, in tumor samples from the MT group of the Local‐SCLC cohort." (PMID 38125769, 2023). "We found that anti-PD-1 treatment reduced tumour growth and increased TIL numbers in GFP-Egr2 knockin mice but had minimal effect on tumour growth in CD2-Egr2/3-/- mice." (PMID 36342511, 2023). "Tumor plasma cells were identified using a combination of markers including CD38, CD138, CD45, CD2, CD14, CD19 and CD56." (PMID 37046814, 2023). "In aggregate, these results show that the interaction between CD2 (T cells) and CD58 (tumor cells) promotes optimal antitumor cytolytic functionality." (PMID 35881486, 2022). "To analyze the magnetic accumulation of PBMCs and their effect on tumor spheroids, we unspecifically stimulated the PBMCs with CD3/CD28/CD2 for 3 days, and loaded them overnight with Cit-SPIONs." (PMID 36497463, 2022). "IL1R1 expression on blood Treg cells and IL1R1− tumour Treg cells was induced after 24 h of stimulation with anti-CD3, anti-CD28 and anti-CD2 beads (anti-CD3/CD28/CD2 beads)." (PMID 35545675, 2022). "The results showed that the expression of CD2, SPN, IL18, PTPRC, GZMA, and TLR7 was upregulated in the tumor group compared with the normal group (p < 0.05)." (PMID 36591509, 2022). "In the TCGA dataset, the expression levels of CD2, HAVCR2, HLA-C, HLA-DRA, HLA-E, KLRK1, and TYROBP were all significantly downregulated in tumor tissues compared with para-tumor tissues." (PMID 35794593, 2022). "The TCGA database showed that the expression of CD2, FGL2, LAT2, and SLAMF1 in tumor tissues was significantly lower than that in cancer tissues, which was confirmed by western blotting experiments." (PMID 35602471, 2022). "To explore the significance of the interaction of these receptors during interaction with tumor cells, we blocked either CD58 (on NALM-6 targets) or CD2/CD244 (on CAR T cells)." (PMID 35881486, 2022). "Immunohistochemistry (IHC) highlighted tumor cells as strongly positive for CD3, CD56, CD5, CD2, CD8, CD4, CD43, T-cell restricted intracellular antigen 1 (TIA-1) and granzyme B. The proliferation index, measured by Ki-67 expression was high with 60%." (PMID 33546043, 2021). "Similar to natural cytotoxic T cells, CD2 ligation is crucial for CAR activation and cytoskeletal rearrangement required for tumor cell killing." (PMID 34809678, 2021).
tumor (continued). "We next explored the association of the expression at an individual transcriptomic level of CD2, CD3D, CD3E, and CXRC6 with the presence of tumor-infiltrating immune cell populations." (PMID 34692491, 2021). "We adjusted these results based on tumor purity, revealing strong and significant correlations between CD96 and CD8+ T cell markers (CD8A), general T cell markers (CD3D, CD3E, CD2), DC markers (HLA-DPB1, HLA-DRA, HLA-DPA1) in LGG." (PMID 33680972, 2021). "Tumor cells in all 20 cases were strongly positive for CD3 and CD7, while CD2(19/20), CD43(19/20), CD8(17/20), and CD56(15/20) were positive for partial tumor cells." (PMID 34895266, 2021). "This study investigated a flow cytometric assay (CD160-ROR1FCA) targeting the tumor-specific antigens CD160 and receptor tyrosine kinase-like orphan receptor 1 (ROR1), along with CD2, CD5, CD19, CD45." (PMID 33344247, 2020). "A possible therapy would be the adoptive transfer of NK cells expressing receptors for these ligands (i.e. NKp30, CD2, or NKG2D) to induce the elimination of residual tumor cells, prevent relapse and improve patient survival." (PMID 29930758, 2018). "The tumor cells have a characteristic phenotype of TCR γ/δ+, βF1−, CD3+, CD2+, CD5−, and CD56+, with a strong expression of cytotoxic proteins." (PMID 29915722, 2018). "Overexpressing CD2 and CD226 on our T cell reporters greatly increased their sensitivity to tumor cells presenting their cognate antigens." (PMID 29707134, 2018). "Using flow cytometry, the expression level of CD2 and CD8α in γδ T cells was evaluated in both PBMC and tumor samples." (PMID 29930558, 2018). "We have adopted this strategy and devised chimeric receptors where CD28-signaling domains were fused to the extracellular binding domains of either CD2, CD226 or TIGIT and thus can be engaged by CD58 or CD155 expressed on the tumor targets." (PMID 29707134, 2018). "To prove that CD11b+Gr-1+ cells directly contributed to tumour progression, we performed adoptive transfer of MDSC sorted from spleen and bone marrow of tumour-bearing Tff2-null mice into AOM/DSS-treated CD2–Tff2 mice." (PMID 26841680, 2016). "This surprising increase of T cell activity from spleens of older hosts due to CD2, CD3ε, CCL19, and CCL5 directly has impacted the decrease in tumor growth we observed in our earlier publication." (PMID 26497558, 2015). "Forexample, in patient 27, whose bone marrow had only one clonalDβ–Jβ rearrangement, the surface of the tumor cells did nothave CD3, CD5, CD4, or CD8, but only CD2 and CD7." (PMID 26483968, 2015). "CD112 (Nectin-2, PVRL2) and CD155 (Necl5, PVR) bind CD226 (DNAM-1), which potentiates in vitro the cytotoxicity of NK cells against a wide range of tumor cells; CD58 (LFA-3) binds CD2 and its co-engagement with ICAM-1 increases NK response." (PMID 26106390, 2015). "Transgenic mice expressing two potent collaborating oncogenes in the germ line (CD2-MYC, -Runx2) develop rapid onset tumours that can be accelerated and rendered polyclonal by neonatal Moloney murine leukaemia virus (MoMLV) infection." (PMID 24586197, 2014). "The tumor cells havecytoplasmatic azurophilic granules and usually show a CD45+bright,CD2+, sCD3-, cytCD3epsilon+,CD56+bright, CD16−/+, cytotoxic granulesmolecules+ phenotype." (PMID 23816348, 2013). "CD2 also influenced metabolic pathways, such as pyrimidine biosynthesis and the urea cycle via CTL‐tumor cell interactions, suggesting its involvement in tumor metabolic reprogramming." (PMID 40859981, 2025). "Unlike the specific case where a lack of CD58 leads to a total loss of CD58-CD2 axis function, in more common scenarios where tumor cells express CD58, the dynamic variation in CD2 expression levels on T cells becomes the primary determinant affecting the axis’s function." (PMID 40615696, 2025).
tumor (continued). "In contrast, the tumor-specific cluster C3 appears less differentiated with features typical of CD56brightCD16neg NK cells (NCAM1, CD2, CD27, SELL, CD69) as well as a signature of tissue residency (CD69 and ITGA1) and of TGF-β-induced genes (SMAD7, TGFB1, PMEP1, SKIL)." (PMID 41145419, 2025). "Notably, the CD2–CD58 interaction, where CD2 is expressed by T cells and CD58 by tumor cells, was significantly elevated, suggesting a key immunoregulatory function." (PMID 40859981, 2025). "According to the IHC results, we found that these tumor cells were all positive for the T-cell antigens CD2 and CD3 and negative for CD8 and CD56." (PMID 40270601, 2025). "Second, could novel CAR constructs that integrate CD2 costimulatory domains while knocking out CD58 and/or CD54 surface molecules perform the dual functions of evading immune rejection and killing tumor cells that lack CD58 expression?" (PMID 40365344, 2025). "Further analysis using a CTL‐MDA‐MB‐231 adhesion assay revealed that the conjugation rate between T cells and MDA‐MB‐231 cells was reduced in the sh‐CD2 CTL group compared with the CTL and sh‐NC CTL groups, indicating impaired CTL‐tumor cell binding due to CD2 silencing." (PMID 40859981, 2025). "In this context, we propose that CD2 regulates CTL activation and may influence their metabolic coupling efficiency, thereby participating in tumor metabolic reprogramming." (PMID 40859981, 2025). "Notably, conventional CAR-T cells preferentially attacked tumor cells with high and medium EGFR, whereas EGFR-BBζ + CD2 CAR-T cells exhibited a markedly reduced bias." (PMID 40615696, 2025). "The absence of CD58 BiTE or the loss of interaction between CD2 and CD58 results in diminished TCE-β-mediated cytotoxicity, T cells activation, and anti-tumor efficacy, constituting a primary mechanism of BiTE resistance." (PMID 40365344, 2025). "In addition, immunohistochemical analysis revealed that tumor cells were positive for CD3, CD43, CD56, TIA1, granzyme B, CD2, CD4, and CD7." (PMID 40433378, 2025). "CD2 downregulation not only directly impairs CTL activation and cytotoxicity but may also indirectly relieve the suppression of CAD expression in tumor cells by reducing IFN‐γ secretion, thereby promoting pyrimidine synthesis." (PMID 40859981, 2025). "In order to evaluate the effect of mIL15 on the production of anti-tumor cytokines, we co-incubated UN-TIL+IL2, TIL-mIL15+IL2, and TIL-mIL15-IL2 cells with anti-CD2/CD3/CD8-conjugated T cell activation magnetic beads and measured the levels of IFN-γ and GZMB in the cell culture supernatant." (PMID 39650651, 2024). "A distinct overexpression of CD1c, CD2, CD3, CD4, CD11c, CD14, CD20, CD44, CD56, CD105, CD146, and CD209 was identified in LCa patients compared to healthy controls, correlating positively with tumor presence." (PMID 38902710, 2024). "CD2 and CD226, primarily on T and NK cells, are crucial for cell adhesion and recognition, known for their role in overcoming T cell exhaustion and boosting anti-tumor responses." (PMID 39349829, 2024). "We show that tumor cells have an increased expression of several markers (CD47, IL7R, NKG7, CD80, CD84, CSF1R, NLRC5/CITA, CD2 and IRF3) that may be involved in regulating the level of immune infiltration and the effect on tumor immunity." (PMID 39001353, 2024). "In hematologic malignancies, there appear to be other adhesion molecules that stabilize the CAR-T/tumor interaction, namely the CD2/CD58 axis, that are not regulated by IFNgR signaling." (PMID 38052854, 2023). "As a result of these measurements in the CT-26 tumor model that was formed in mice, a non-significant statistical difference in tumor sizes was observed in the 5FU/IL2/CD2 nanoplex groups when compared with the control group (p > 0.05)." (PMID 36839637, 2023).